INS (insulin)
Diseases named in the same sentence as INS in open-access papers (continued):
Sharing a sentence is not in itself a finding about the gene and the disease.
diabetes (continued). "However, this is followed by a rapid onset of β-cell dysfunction (downregulation of insulin expression) and β-cell apoptosis that quickly progresses to diabetes." (PMID 33239359, 2021). "Of participants with diabetes, 71.4% used oral glucose lowering drugs, 20.3% used insulin." (PMID 34134731, 2021). "However, differentiation of embryonic stem cells (ESCs) or induced pluripotent stem cells (IPSCs) to insulin-secreting cells by mimicking the intercellular signaling during the β cells development, is an ambitious hope for cell therapy in diabetes." (PMID 33686020, 2021). "While based on studies of more than a decade ago, the medications used—including metformin, sulfonylureas, and insulin—are still the mainstay of glucose management in Brazil ́s national health system as well as in the care of diabetes in most settings around the world." (PMID 34362211, 2021). "For children that chose to stay virtual for the 20202021 school year, the school nurse still called the families of the children with diabetes at mealtimes, to make sure they were checking the blood sugar at lunch and giving the proper insulin dosage, which seemed to help." (PMID 34020722, 2021). "Also, up-expression of SOX4 in diabetic islets was closely related to the reduced insulin secretion and diabetes development, indicating that high expression of SOX4 gene was correlated positively with the risk of diabetes." (PMID 34386303, 2021). "It is conceivable that PCSK9 may impair EPC by modifying insulin secretion and metabolic control, or vice versa that the metabolic derangement of diabetes may alter PCSK9 levels, in turn affecting EPC number." (PMID 33958634, 2021). "The negative impact of diabetes on the lungs is observed in human epidemiological studies as higher fasting insulin and insulin resistance is associated with worsening pulmonary function testing." (PMID 34375359, 2021). "Animal experiments showed that the level of blood glucose in rats with diabetes dropped considerably (comparable to an s.c. injection of insulin) at 4 h and 6 h following the combined application of positive nanovesicles driven by iontophoresis and microneedles." (PMID 33466845, 2021). "Type 1 diabetes mellitus (T1DM) is an insulin-dependent, multifactorial autoimmune disease, which results in degradation of the beta cells of the islets of Langerhans, which causes impaired insulin production and secretion." (PMID 33918177, 2021). "Furthermore, of those that had been told they had elevated blood sugar or diabetes, 41% (n = 25/61) reported taking insulin." (PMID 33798234, 2021). "Furthermore, FFA and triglyceride levels were reduced in patients with diabetes and serum insulin decreased in prediabetic subjects." (PMID 34970150, 2021). "Insulin, upon discovery, represents lifesaving therapeutic for people suffering from diabetes." (PMID 34203830, 2021). "Insulin and oral antidiabetic medication are used to treat diabetes." (PMID 34970629, 2021). "Patients with diabetes went on to be treated with insulin purified from cattle or pigs." (PMID 34717951, 2021). "Mean diabetes duration was 17 ± 10 years and 55.5% of the patients were treated with insulin." (PMID 34819079, 2021). "One of the hallmarks of diabetes is resistance of cells to the action of insulin." (PMID 34299151, 2021). "Patients with a long diabetes duration were older and more likely to use insulin." (PMID 34378729, 2021). "The major challenges voiced by patients at baseline were related to poor access due to the costs of transport for monthly visits and medications, and fragmentation of diabetes care between primary care, laboratories and district health offices which store insulin." (PMID 33777712, 2021). "In addition, some patients with T2DM, especially in low- and middle-income countries (LMICs), will require insulin to control their diabetes." (PMID 35095504, 2021). "Converting α cells into insulin-producing cells could provide a promising therapeutic strategy to cure diabetes." (PMID 34882233, 2021).
diabetes (continued). "Although the mechanism that links IGSF3 to diabetes is unclear, there were several observations that makes IGSF3 an interesting candidate to study further, including strong correlations with insulin and liver fat, as well as the responsiveness to diabetes treatment." (PMID 33279861, 2021). "In addition, the use of Insulin increased significantly with increasing duration of diabetes with 79.6% of the people who have had diabetes for more than 10 years on insulin." (PMID 33961671, 2021). "It has been suggested that SOX4, which is overexpressed in diabetes, may reduce insulin secretion by impairing fusion pore expansion." (PMID 33937248, 2021). "Diabetes drastically spreads due to the patient's inability to use the produced insulin." (PMID 34631003, 2021). "Additionally, compared to the CSF of normal subjects, a decreased CSF insulin in type-2 diabetes mellitus patients (insulin resistance state) was noticed, which can be explained by decreased transport across the blood-brain barrier." (PMID 34877187, 2021). "Puberty has been shown to be associated with a decrease in insulin-stimulated glucose metabolism in patients with and without diabetes." (PMID 34778146, 2021). "Only 89 (6.1%) physicians were taking insulin for the treatment of diabetes mellitus." (PMID 34104603, 2021). "Rosiglitazone is widely used for the treatment of diabetes as it increases insulin sensitivity." (PMID 34140896, 2021). "Therefore, human birthweight is a bioassay of inherent insulin secretory capacity, and monogenic disorders of insulin secretion provide unique insights into the genetic link between lower birthweight and diabetes resulting from reduced insulin secretion." (PMID 33569631, 2021). "The mechanisms behind this association might be extensive toxic results, mediated through adiponectin, insulin, and inflammation or indirect effects of hypertension or diabetes." (PMID 33921359, 2021). "Of these symptoms, in our experimental set-up, only glucose intolerance and hyperinsulinemia support the hypothesis of a pseudo-diabetes state in the HF_CR mice as they did show normoglycemia and recovered insulin sensitivity after 6 weeks of PCCI." (PMID 34736458, 2021). "Consequently, these studies showed a positive impact of oral anti-diabetes medication, as well as insulin in limiting the progression of dementia and promoting cognitive status." (PMID 34877187, 2021). "Although there is a large body of evidence demonstrating an association between diabetes and cognitive decline or dementia, most studies focus on hyperglycemia and cognition but do not discuss insulin levels or insulin resistance." (PMID 34577866, 2021). "Diabetes mellitus (DM) is a set of metabolic disorders characterised by hyperglycaemia, caused by a lack of insulin release as well as its activity." (PMID 34616293, 2021). "In total, digital diabetology has a huge potential to improve the health and QoL of patients with DM, especially glycemic control and diabetes therapy, using glucose monitoring systems, insulin pens, insulin pumps, closed-loop systems, mHealth apps, telemedicine, and EMR." (PMID 33759789, 2021). "Consequently, most diabetes research is aimed at understanding the molecular and cellular bases of pancreatic development, islet formation, β-cell survival, and insulin secretion." (PMID 34201511, 2021). "Based on these results, we propose that one of the mechanisms by which OP alleviates diabetes may be the activation of the insulin signaling pathway and the inhibition of the mRNA expression of Fbp1 in the liver of db/db mice." (PMID 34206641, 2021). "Similarly, the diabetes gene Arl15 was described to improve insulin-mediated AKT phosphorylation in myotubes." (PMID 34445304, 2021). "This score would be reviewed by health care professionals and could be used as a reference to inform adjustments on medical treatments (diabetes medications and insulin dosing requirements) for PWD." (PMID 33918343, 2021).
diabetes (continued). "Another study conducted in London, UK, also reported that diabetes mellitus, hypertension, high serum insulin levels, low HDL cholesterol levels, and high plasma triglyceride levels were more prevalent in South Asian Indian immigrants than those of European descent." (PMID 34650849, 2021). "The cells co-expressing insulin and glucagon may be pancreatic alpha cells or progenitor cells, which are known to be increased in certain disease conditions including obesity, diabetes, and inflammation as well as in the course of their development." (PMID 33809267, 2021). "Conversely, in type 2 diabetes mellitus model, a hyper-insulin environment, both in vivo and in vitro experiments indicate that KLF5 attenuates VEGF-induced endothelial migration and proliferation and compromises angiogenic function by inhibiting the expression of NOS3." (PMID 33493334, 2021). "Additionally, it has been shown that siRNA-mediated ARL15 depletion in a human β cell line (EndoC-βH1) reduces insulin secretion, further linking this gene to diabetes traits." (PMID 34779483, 2021). "Today, diabetes technologies, such as continuous glucose monitoring and mobile glucose monitoring, can support HbA1c management by transmitting glucose levels to patients and clinicians and provide real-time insulin dose recommendations." (PMID 33533725, 2021). "To examine this hypothesis, we conducted this study to examine the effect of CR on whole-body glucose tolerance and blood insulin levels with its related proteins in the late stage of diabetes." (PMID 33916828, 2021). "AMA may have effects for diabetes and inflammation because of the involvement of insulin and GR signaling pathways." (PMID 34065446, 2021). "Diabetes and insulin signaling pathways were also identified by the pathway enrichment analysis." (PMID 34535768, 2021). "Overall, 51.6% of patients had type 2 diabetes mellitus and received OADs or insulin." (PMID 34255798, 2021). "Immunotherapies such as PD/PD-L and CTLA-4 inhibitors can reduce the production of insulin from islet cells as in type 1 diabetes mellitus, whereas targeted treatments such as PI3K/mTOR inhibitors can induce insulin resistance similar to that seen in type 2 diabetes mellitus." (PMID 34830886, 2021). "Interestingly, in one rat in the delayed diabetes group, which developed hyperglycemia at 78 days of age, one third of the islets still contained insulin+ cells accounting, on average, for 32% of islet cells." (PMID 33815287, 2021). "Therefore, restoration of pancreatic insulin-producing β cells is vital for treating diabetes and preventing its complications." (PMID 34054538, 2021). "Dysregulation of insulin production raises blood glucose levels, leading to diabetes onset." (PMID 34294685, 2021). "In diabetes, galectin-3 may mediate b-cell fibrosis through an inflammatory pathway, leading to impaired insulin secretion." (PMID 35141299, 2021). "Using the bolus approach, only healthy pigs reached hypoglycaemic target while the diabetic group showed a variable response to the insulin bolus, reflecting variation in initial fasted plasma glucose and insulin sensitivity among animals in this STZ induced diabetes model." (PMID 33727615, 2021). "Studies in human subjects have identified increased FGF-21 levels in cardiometabolic pathologies such as non-alcoholic fatty liver disease, coronary artery disease, diastolic heart failure, diabetes, and insulin resistance, mediating the adaptive response to various stresses." (PMID 33535425, 2021). "However, the current therapeutic strategies for diabetes mainly focus on the control of glucose and lipid metabolism, and it is difficult to fundamentally improve insulin resistance and tissue repair." (PMID 33588950, 2021).
diabetes (continued). "In diabetes, intrinsic genetic and epigenetic factors, as well as extrinsic factors, including circulating levels of lipids, glucose, or amino acids, can disrupt the insulin signaling network in insulin-sensitive tissues, leading to insulin resistance." (PMID 34208379, 2021). "However, there were significantly increased trend in the percentage of the subjects receiving insulin therapy with increased age (p = 0.039 for trend) and prolonged duration of diabetes (p < 0.001 for trend)." (PMID 33598483, 2021). "Diabetes mellitus (DM) is a disease caused by lack of insulin secretion or insulin resistance, which cause the body to experience persistent hyperglycemia and long-term metabolic disorders." (PMID 34770958, 2021). "Promoting islet β‐cell regeneration and restoring endogenous insulin secretion may present an ideal approach to curing diabetes." (PMID 33660433, 2021). "Our results showed that patient's aged 31-35 and 41-45 years, with diabetes for 6-10 years, on insulin therapy, and hospitalized for hypoglycaemic episodes in the preceding six months were more likely to have poor mental wellbeing, diabetes-related emotional distress, and have fear of hypoglycaemia." (PMID 34646639, 2021). "As a chronic distress exposure and stress, low perceived social support was associated with physiological alterations (e.g., activate the hypothalamic–pituitary–adrenal axis and sympathetic nervous system), which contributes to insulin resistance and poorer diabetes-related health." (PMID 34772424, 2021). "Strict storage recommendations for insulin are difficult to follow in hot tropical regions and even more challenging in conflict and humanitarian emergency settings, adding an extra burden to the management of people with diabetes." (PMID 33534816, 2021). "T2D is a metabolic disease of abnormal insulin function that leads to chronic hyperglycemia and impacts roughly 26 million individuals in the United States, with an estimated additional 79 million facing pre-diabetes conditions." (PMID 34497507, 2021). "In addition, young-onset T2DM faces some challenges in diabetes management, such as the complexity of drug treatment, acceptance of insulin therapy, adherence to blood glucose monitoring, social stigma, and job stress." (PMID 34822452, 2021). "Besides, polysaccharides directly present anti-diabetes activities; some polysaccharide and natural nanoparticles have been developed as oral drug delivery systems for insulin delivery." (PMID 34071638, 2021). "Our findings could provide clinical guidance for insulin treatment in patients with COVID-19 and diabetes." (PMID 34367067, 2021). "The development of new biosimilar insulin products over the last few years, including rapid-acting insulins like reported here, has the potential to reduce drug treatment costs and thereby facilitate greater access of insulin treatment for people with diabetes." (PMID 34824344, 2021). "Insulin is used to therapeutically lower high glucose in individuals with type 1 and long-standing type 2 diabetes; however, this commonly results in iatrogenic hypoglycaemia, one major barrier in achieving and maintaining normal glucose control in diabetes." (PMID 34814734, 2021). "Transiently elevated lactate obtained during physical exercises improves insulin resistance to peripheral tissues whereas chronical hyperlactatemia might indicate the early stages of prediabetes and contributes to the onset of diabetes." (PMID 33708999, 2021). "Mechanisms that regulate the cleavage of IR by BACE1 in the liver during diabetes may constitute targets to improve insulin sensitivity." (PMID 34029592, 2021). "Higher rates of adverse outcomes in patients with diabetes mellitus may be due to adverse effects of insulin therapy, inflammatory response, and hormonal overreaction which leads to disruption of cardiovascular function." (PMID 34961534, 2021).
diabetes (continued). "Interestingly, our findings indicated that WVBF treatment exert a protective role in diabetes by affecting insulin signaling cascade." (PMID 34899339, 2021). "In Agouti mutation model that produces marked obesity without diabetes in the dam, adult female offspring show glucose intolerance associated with insulin secretion defect in beta-cells." (PMID 35111136, 2021). "Diabetes (Diabetes Mellitus, DM) is a group of metabolic diseases that chronically increase blood glucose levels due to defective insulin secretion or impaired biological effects, and is mainly divided into type 1 (insulin-dependent, T1DM) diabetes and type 2 (non-insulin-dependent, T2DM) diabetes." (PMID 34604109, 2021). "While the number of patients with diabetes has continuously increased worldwide, current treatment methods (self-injection of insulin) are unfavorable due to inherent issues of injectable formulations, such as immune reactions, infections, pain, and discomfort." (PMID 33422063, 2021). "Furthermore, this cohort also had higher rates of preoperative systemic inflammatory response syndrome (SIRS), diabetes, insulin usage, dyspnea, chronic obstructive pulmonary disease (COPD), and steroid usage." (PMID 35003975, 2021). "While most studies illustrated the pervasive impact of the child’s diabetes on parents’ lives, two studies highlighted how using an insulin pump could alleviate some of the stresses and constraints they experienced." (PMID 33814007, 2021). "For Type 2 diabetes (E11) these words are either related to the use of medication (“metformin”, “gliclazide”, “insulin”), are synonyms for E11 (“diabetes”, “mellitus”, “dmii”) or are words that co-occur with cardiovascular risk factors (“overweight” (translation: overweight), “stenoses”)." (PMID 33637859, 2021). "Our observation that the Sam68 deletion lowers blood-glucose levels, and promotes insulin sensitivity by decreasing the stability of CRTC2 protein, suggests that these two molecules may also have a role in the pathogenic mechanisms of diabetes." (PMID 34099657, 2021). "Moreover, most microneedles are applied in biomedical areas, especially for cancer therapy, skin disease therapy, insulin delivery for diabetes treatment, blood glucose level detection and vaccines." (PMID 34641460, 2021). "The purpose of this study was to elucidate the mechanisms that regulate BACE1-dependent cleavage of IR during diabetes to identify regulatory steps that could be pharmacologically targeted to reduce IR cleavage and improve insulin sensitivity." (PMID 34029592, 2021). "The results of their study showed that rats with diabetes had a significant increase in plasma glucose, HbA1c, and hexokinase levels and decreased insulin and peptide C, glycogen (liver and muscle), and glucose 6 phosphatase activity in the liver and kidneys compared with healthy mice." (PMID 33546744, 2021). "The most prevalent kind of diabetes is type 2 diabetes mellitus, which is characterized by the imbalance between insulin production and blood sugar absorption, resulting in a greater risk of both acute and long-term complications, as well as mortality at a younger age." (PMID 34451737, 2021). "Type 1 diabetes mellitus (T1DM) is associated with impaired β cell mass.The pathogenesis of type 2 diabetes is more variable, and it consists of insulin resistance and defective insulin secretion." (PMID 34194388, 2021). "Furthermore, we demonstrated its beneficial effects in a chronic insulin-controlled diabetes model including protection against streptozotocin-induced beta cell damage and some microvascular complications, such as neuropathy and retinopathy." (PMID 34209525, 2021). "Our study has several limitations, which include the lack of information regarding the patient’s condition at discharge, laboratory values or test results, description of treatment, use of insulin, hemoglobin A1C, hypoglycemia events, blood glucose at admission, and diabetes complications." (PMID 34945110, 2021).